CYGB (cytoglobin)
Diseases named in the same sentence as CYGB in open-access papers (continued):
Sharing a sentence is not in itself a finding about the gene and the disease.
head and neck squamous cell carcinoma (4 papers, 2009 to 2022). A squamous cell carcinoma that arises from any of the following anatomic sites: lip and oral cavity, nasal cavity, paranasal sinuses, pharynx, larynx, and salivary glands. "Cytoglobin expression and promoter methylation were investigated in sporadic head and neck squamous cell carcinoma (HNSCC) using a cross-section of clinical samples." (PMID 19568272, 2009). "Our recent study of CYGB promoter methylation in head and neck squamous cell carcinoma (HNSCC) using quantitative pyrosequencing methylation analysis (PMA) shows that methylation is both common (65% of cases) and significantly tumour-specific (P=0.02) in cancers at this site." (PMID 19568272, 2009).
hepatocellular carcinoma (4 papers, 2009 to 2023). A malignant tumor that arises from hepatocytes. "The ongoing controversy of the role of CYGB has been recently highlighted by recent suggestions of its function as a tumour suppressor gene in NSCLC and HNSCC, and as a prospective gene therapy in the prevention of hepatocellular carcinoma after liver cirrhosis." (PMID 19568272, 2009).
melanoma (4 papers, 2014 to 2024). A malignant, usually aggressive tumor composed of atypical, neoplastic melanocytes. "Collectively, our results suggest a cytoprotective role of CYGB in the cellular response to ferroptosis in melanoma via the interplay of ferroptosis and pyroptosis cell death pathways." (PMID 36009267, 2022). "Although CYGB is expressed in many different cell types and tissues, CYGB is particularly highly enriched in pigment-producing melanocytes and frequently downregulated during melanocyte-to-melanoma transition." (PMID 36009267, 2022). "A potential effect of CYGB knockdown in G361 melanoma cells on the intracellular ROS levels was assessed using the fluorescent dye H2DCF-DA." (PMID 36009267, 2022). "Considering the homology to Mb and their very similar oxygen affinity, we sought to investigate a potential effect of CYGB knockdown in G361 melanoma cells on mitochondrial respiration." (PMID 36009267, 2022). "To investigate the role of CYGB in melanoma cells, we first established an shRNA-mediated CYGB knockdown cell line (G361-shCYGB) as well as a knockdown control line (G361-shCTR)." (PMID 36009267, 2022). "In this study, we investigated the potential effect of CYGB on the cellular sensitivity towards RSL3-mediated ferroptosis in G361 melanoma cells that express highly abundant endogenous levels of CYGB." (PMID 36009267, 2022). "Our results display that B2M and YWHAZ represent the most optimal reference genes to reliably quantify hypoxia-inducible CYGB expression in melanoma cell lines." (PMID 34035373, 2021). "This study aimed to select the optimal reference genes to study CYGB expression levels in melanoma cell lines exposed to hypoxic conditions (0.2% O2) and to the HIF prolyl hydroxylase inhibitor roxadustat (FG-4592)." (PMID 34035373, 2021). "We further validate hypoxia-inducible CYGB expression on protein level and by using CYGB promoter-driven luciferase reporter assays in melanoma cell lines." (PMID 34035373, 2021). "In this study we selected and validated the most appropriate reference genes for analysis of CYGB gene expression in two melanoma cell lines (A375 and Malme-3M) under hypoxic conditions using geNorm and NormFinder algorithms." (PMID 34035373, 2021). "The level of protein expression in melanocytes was comparable to, or even higher than, the four CYGB expression-positive melanoma cell lines." (PMID 24722418, 2014). "We observed a significantly increased proliferation rate as a result of CYGB knockdown in the CYGB siRNA-treated cells, providing strong evidence for the tumor suppressor properties of the CYGB gene in melanoma." (PMID 24722418, 2014). "Of these cell lines, a high amount of CYGB mRNA was expressed exclusively in melanoma cells, including G361 and C32." (PMID 24722418, 2014). "A relatively high expression level of CYGB mRNA was apparent in 7 out of 8 normal melanocyte cell lines, but only 14 melanoma tumor tissues out of specimens from 79 melanoma patients (17.7%) reached the same level." (PMID 24722418, 2014). "The nuclear localization of CYGB appears to be rather specific to melanoma cells, compared with melanocytes." (PMID 24722418, 2014). "The RNA interference-mediated knockdown of the CYGB transcript in CYGB expression-positive melanoma cell lines resulted in increased proliferation in vitro and in vivo." (PMID 24722418, 2014). "As expected, some melanoma cells including A375, SKMEL28 and HS294T formed a group that expressed CYGB mRNA levels that were as low as those of non-melanoma cell lines." (PMID 24722418, 2014). "The unexpected identification of CYGB in melanoma cells prompted us to examine the presence of CYGB in melanocytes, the precursor of melanoma cells." (PMID 24722418, 2014). "Bisulfite-modified genomic sequencing revealed that several melanoma cell lines that abrogated CYGB expression were found to be epigenetically regulated by hypermethylation in the promoter region of CYGB gene." (PMID 24722418, 2014).
melanoma (continued). "Several melanoma cells that escaped from epigenetic regulation were shown to have considerable expression levels of CYGB, retaining their melanocytic character." (PMID 24722418, 2014). "In view of these unique melanoma properties, the elevated production of ROS seems to be a melanoma-specific defect, which could be caused by the heavy oxidation of melanin and possibly by CYGB down-regulation for some cell types, as has been shown in the present study." (PMID 24722418, 2014). "CYGB expression in (metastatic) melanoma tissues could be used as a biomarker for determining the best therapeutic approach and treatment outcome." (PMID 36009267, 2022). "Thus, whilst the knockdown of CYGB in G361 melanoma cells gives rise to a more malignant cancer phenotype, it also makes cells more susceptible to ferroptosis." (PMID 36009267, 2022). "Finally, we validated these reporter gene assays in a non-melanoma cancer line and used Hep3B hepatocarcinomatous cells, in which CYGB mRNA levels were shown to be strongly induced under hypoxic conditions." (PMID 34035373, 2021). "Melanocytes, the primary origin of melanoma, also expressed CYGB at a high level." (PMID 24722418, 2014). "If CYGB acts as a ROS scavenger in melanoma cells, it may alleviate the high levels of oxidative stress." (PMID 24722418, 2014). "CYGB, like other hexacoordinated globins, may scavenge ROS utilizing heme and thiol residues and could well be a target for gene silencing in melanoma." (PMID 24722418, 2014). "To clarify whether CYGB also functions as a tumor suppressor gene in CYGB-positive melanoma cells, we silenced the CYGB gene in G361 and C32TG cells using specific siRNA." (PMID 24722418, 2014). "We searched the database (GSE29359) to determine whether fluctuations in cytoglobin expression levels, as observed between the G361 and A375 cell lines, are common among melanoma patients." (PMID 24722418, 2014). "The presented approach of normalizing hypoxia-inducible CYGB gene expression will be of major interest for further studies focussing on the importance and functional implications of hypoxic CYGB regulation and how this may impact melanoma cell survival, growth and spreading." (PMID 34035373, 2021). "In addition, present study indicates that CYGB could be a possible candidate biomarker to predict the malignant potential of melanomas." (PMID 24722418, 2014). "In this study, we investigated the potential effect of CYGB on the cellular sensitivity towards (1S, 3R)-RAS-selective lethal small molecule (RSL3)-mediated ferroptosis in the G361 melanoma cells with abundant endogenous expression." (PMID 36009267, 2022). "In 2 melanoma cell lines (A375, MEWO), on the other hand, CYGB mRNA was detected at much lower levels." (PMID 24722418, 2014). "Unexpectedly, we found that several, but not all, melanoma cell lines expressed CYGB mRNA and protein at much higher levels than cells of other origins." (PMID 24722418, 2014). "Whether or not CYGB is lost during the melanocyte-to-melanoma transition may affect tumor malignancy." (PMID 24722418, 2014). "Thus, CYGB appears to play a tumor suppressive role as a ROS regulator, and its epigenetic silencing, as observed in CYGB expression-negative melanoma cell lines, might function as an alternative pathway in the melanocyte-to-melanoma transition." (PMID 24722418, 2014).
colon cancer (3 papers, 2015 to 2023). "An obviously elevated ROS level was observed in both colon cancer cell lines that overexpressed CYGB." (PMID 33611811, 2021). "Thus, our findings emphasize the importance of CYGB in ferroptosis regulation in colon cancer cells." (PMID 33611811, 2021). "Finally, high expression level of CYGB had the close correlation with key genes YAP1 and ACSL4 in ferroptosis pathway in colon cancer based on analysis from TCGA data." (PMID 33611811, 2021).
liver cancer (3 papers, 2022 to 2024). An epithelial or non-epithelial malignant neoplasm that arises from the liver. "The cytoglobin knockout mice has been shown to spontaneously develop multiorgan cancer with aging and exhibit increased susceptibility to carcinogenesis in a liver cancer model." (PMID 39316687, 2024). "Moreover, investigations into liver cancer development revealed that CYGB-deficient mice exhibited heightened susceptibility to liver cancer induction in both chemically induced and high-fat diet models." (PMID 39227479, 2024). "Furthermore, CYGB-deficient mice rapidly develop liver cancer in both chemically induced and high-fat diet models." (PMID 35504863, 2022).
oesophageal cancer (3 papers, 2006 to 2012). "CYGB is a candidate tumour-suppressor gene on chromosome 17q and is the only gene completely contained within the 42.5 kb Tylosis with Oesophageal Cancer minimal region." (PMID 16449996, 2006). "Cytoglobin is a candidate for the tylosis with oesophageal cancer gene, and its expression is strongly down-regulated in non-cancerous oesophageal biopsies from patients with TOC compared with normal biopsies." (PMID 22359545, 2012). "Cytoglobin (CYGB) is a candidate tumour-suppressor gene on chromosome 17q25 and is the only gene completely contained within the 42.5-kb Tylosis with Oesophageal Cancer (TOC) minimal region." (PMID 19568272, 2009). "The 17q25 TOC minimal region is subject to frequent allelic imbalance in sporadic oesophageal cancer and CYGB is dramatically downregulated in affected (non-malignant) tylotic oesophageal tissue compared with normal oesophagus." (PMID 19568272, 2009). "When cytoglobin was overexpressed in TE-8 oesophageal cancer cell lines, which have little or no endogenous cytoglobin expression, consistent with previous studies we observed statistically significant protection from BSO-induced oxidative DNA damage as assessed by the FPG-modified comet assay." (PMID 22359545, 2012). "In the current study, we tested this hypothesis by manipulating cytoglobin expression in both normal and oesophageal cancer cell lines, which have normal physiological and no expression of cytoglobin respectively." (PMID 22359545, 2012). "The mechanism of downregulation of CYGB in TOC is unclear, as no mutations have been identified in affected tissue, although there is evidence that CYGB promoter methylation may occur in sporadic oesophageal cancer and possibly also in ovarian cancer." (PMID 19568272, 2009).
oral cancer (3 papers, 2006 to 2021). "In conclusion, we present evidence that cytoglobin expression results in important phenotypic changes to oral carcinoma cells and confers resistance to cisplatin-induced apoptosis." (PMID 33441751, 2021). "The role of CYGB as a tumour suppressor gene in oral cancer is also novel and awaits further investigation." (PMID 16449996, 2006). "We also investigated the CYGB and HIF1A response of human oral cancer cell lines to hypoxic conditions." (PMID 19568272, 2009).
ovarian carcinoma (3 papers, 2006 to 2021). A malignant neoplasm originating from the surface ovarian epithelium. "Chen’s study revealed that, in ovarian cancer cell line treated with CYGB siRNA resulted in an increase in cell proliferation." (PMID 33958959, 2021).
pancreatic cancer (3 papers, 2022 to 2025). "In conclusion, we found that CYGB expression in PSCs was associated with reduced pancreatic tumor development and cancer cell proliferation, migration, and colony formation." (PMID 35504863, 2022). "The decrease of CYGB expression results in pancreatic cancer cell resistance to ferroptosis, which makes them more resistant to chemotherapy." (PMID 42290659, 2025). "CYGB expression appeared predominately in the area surrounding adenocarcinoma and negatively correlated with tumor size in patients with pancreatic cancer." (PMID 35504863, 2022). "Here, we demonstrate that high expression of iron-responsive element binding protein (IRP1)/A + T rich interaction domain protein 3a (ARID3A) inhibits ferroptosis and enhances chemoresistance of pancreatic cancer cells via handling the promoter region of a ferroptosis gene, cytoglobin (CYGB)." (PMID 42290659, 2025). "Here, we examined the role of CYGB in the development of pancreatic cancer." (PMID 35504863, 2022). "CYGB was not expressed in CD31-positive endothelial cells or AE1/AE3-positive pancreatic carcinoma." (PMID 35504863, 2022).
colorectal cancer (2 papers, 2021 to 2024). A primary or metastatic malignant neoplasm that affects the colon or rectum. "In the present study, we demonstrated that CYGB inhibits colorectal cancer (CRC) cell growth and promotes lipid peroxidation." (PMID 33611811, 2021). "Importantly, ferroptotic features with accumulated lipid ROS and malondialdehyde were observed in CYGB‐overexpressing colorectal cancer cells." (PMID 33611811, 2021).
liver cirrhosis (2 papers, 2009 to 2026). "Based on these findings, therapeutic strategies employing recombinant CYGB for the treatment of human liver cirrhosis are currently being explored, and their potential clinical applications are eagerly anticipated." (PMID 41897531, 2026).
osteosarcoma (2 papers, 2018 to 2021). A usually aggressive malignant bone-forming mesenchymal neoplasm, predominantly affecting adolescents and young adults.
tylosis (2 papers, 2012 to 2023). "Furthermore, most cancer cells have a reduced expression of CYGB, with a dramatic decrease (70%) of CYGB expression reported in tylosis with esophageal cancer." (PMID 36112670, 2023).
acute myocardial infarction (1 paper, 2017). Necrosis of the myocardium, as a result of interruption of the blood supply to the area. "Future studies will require to examine the in vivo survival capacity of hCPCs upon upregulation of CYGB, and conduct a thorough analysis of the molecular mechanisms underlying the potential cytoprotective function of CYGB following acute myocardial infarction." (PMID 28883470, 2017).
atherosclerosis (1 paper, 2018). A disease characterized by the build-up of fatty material and calcium deposition in the arterial wall resulting in partial or complete occlusion of the arterial lumen. "The results of these gene-based analyses need to be replicated in other data sets, but tentatively suggest CYGB as an interesting candidate gene, especially given increasing recognition of the important role of smooth muscle cells in atherosclerosis." (PMID 30003307, 2018).
bladder cancer (1 paper, 2024). "Therefore, SOX7 and CYGB may play an important role in the progression of bladder cancer, and they can be used as prognostic markers of bladder cancer patients." (PMID 39227479, 2024).
breast tumor (1 paper, 2018). "Higher promoter methylation levels associated with lower CYGB expression was seen in the 36 breast tumor-normal tissue pairs from TCGA dataset." (PMID 30545372, 2018). "(B) Representative images of MSP for detecting CYGB promoter methylation in 195 breast tumor tissue samples and 16 surgical margin tissue samples." (PMID 30545372, 2018). "Compared with that in breast tumor adjacent tissues, CYGB expression was significantly lower in breast tumor samples." (PMID 30545372, 2018).
cervix carcinoma (1 paper, 2021). "In line with our data, several studies reported that CYGB is upregulated under strong hypoxic conditions in Hep3B, renal clear cell carcinoma (RCC4), transformed human bronchial epithelial cells (BEAS-2B), human cervix carcinoma (HeLa) and murine derived hippocampal neurons (HN33) cells." (PMID 34035373, 2021).
esophageal tumors (1 paper, 2014). "Recent methylation-specific PCR assays have provided evidence of higher levels of CYGB promoter methylation in lung and esophageal tumors compared with adjacent nonmalignant tissues." (PMID 24722418, 2014).
Hypertension (1 paper, 2017). The presence of chronic increased pressure in the systemic arterial system. "Here, the authors show that nitric oxide is degraded by the enzyme cytoglobin in the vascular wall, and that mice lacking cytoglobin have reduced blood pressure and are less sensitive to angiotensin-mediated hypertension." (PMID 28393874, 2017).
ischemic heart disease (1 paper, 2017). "It provides a rationale for the exploration of the CYGB pathway as a molecular target that can be used to enhance the effectiveness of cardiac stem/progenitor cell therapy for ischemic heart disease." (PMID 28883470, 2017).
keloid (1 paper, 2021). An irregularly shaped, elevated mark on the skin caused by deposits of excessive amounts of collagen during wound healing. "The aim of the present study was to explore whether the inhibition of CYGB expression caused impaired mitochondrial function of keloid fibroblasts." (PMID 33958959, 2021). "We concluded that mitochondrial function is impaired in the inhibition of CYGB expression with siRNA in keloid fibroblasts, as indicated by decreased PGC-1α expression and the activity of the SDH enzyme, both of which are markers of mitochondrial function." (PMID 33958959, 2021). "The decrease in PGC-1α protein levels is thought to be a result of suppression of CYGB expression in keloid fibroblasts." (PMID 33958959, 2021). "Hitherto, the role of CYGB in the metabolism of fibroblasts in keloid has not been reported." (PMID 33958959, 2021).
kidney injury (1 paper, 2024). Trauma to the kidney. "This study is the first to examine the significance and implications of the Nrf2/HO-1 and cytoglobin pathways in the protective efficacy of IAA and CDCA against VPA-induced kidney injury." (PMID 39759289, 2024).
non-alcoholic fatty liver disease (1 paper, 2021). "Using the set of 3346 significantly up-regulated transcripts in cytoglobin expressing cells, key pathways identified included “non-alcoholic fatty liver disease” (2.2-fold enrichment) and “oxidative phosphorylation” (1.9-fold enrichment)." (PMID 33441751, 2021).
oral squamous cell carcinoma (1 paper, 2021). "Cytoglobin is important in the progression of oral squamous cell carcinoma but the molecular and cellular basis remain to be elucidated." (PMID 33441751, 2021).